PPP3CB (protein phosphatase 3 catalytic subunit beta)
Description:
Calcium-dependent, calmodulin-stimulated protein phosphatase which plays an essential role in the transduction of intracellular Ca(2+)-mediated signals. Dephosphorylates TFEB in response to lysosomal Ca(2+) release, resulting in TFEB nuclear translocation and stimulation of lysosomal biogenesis. Dephosphorylates and activates transcription factor NFATC1. Dephosphorylates and inactivates transcription factor ELK1. Dephosphorylates DARPP32. Negatively regulates MAP3K14/NIK signaling via inhibition of nuclear translocation of the transcription factors RELA and RELB (By similarity). May play a role in skeletal muscle fiber type specification (By similarity).
Synonyms: CALNA2; CALNB; CNA2; PP2Bbeta
Tractability: Antibody: its Gene Ontology location is reachable by antibodies, with medium confidence. PROTAC: ubiquitination databases record sites on it; its protein half-life has been measured; a small molecule that binds it is known.
Target class: Protein Phosphatase; Phosphatase; Serine/threonine protein phosphatase; Enzyme
Gene: Protein-coding gene on chromosome 10 (73,436,418 to 73,496,026, reverse strand). Ensembl gene ENSG00000107758.
Subcellular location: Cytoplasm
Subcellular location (Human Protein Atlas): Cytosol; Calyx; Nucleoplasm
Pathways (Reactome):
Immune System: CLEC7A (Dectin-1) induces NFAT activation; Calcineurin activates NFAT; FCERI mediated Ca+2 mobilization
Signal Transduction: Ca2+ pathway; DARPP-32 events
Developmental Biology: ROBO receptors bind AKAP5
Gene Ontology:
Molecular function: calcium ion binding; calmodulin binding; calmodulin-dependent protein phosphatase activity; enzyme binding; protein binding; protein dimerization activity; protein phosphatase 2B binding; protein serine/threonine phosphatase activity; hydrolase activity
Biological process: calcineurin-mediated signaling; calcineurin-NFAT signaling cascade; positive regulation of lysosome organization; positive regulation of protein localization to nucleus; positive regulation of transcription by RNA polymerase II; protein dephosphorylation; axon extension; calcium-ion regulated exocytosis; dephosphorylation; learning; memory; negative regulation of calcium ion import across plasma membrane; negative regulation of signaling; positive regulation of calcineurin-NFAT signaling cascade; positive regulation of calcium ion import across plasma membrane; positive regulation of DNA-templated transcription; positive regulation of insulin secretion involved in cellular response to glucose stimulus; protein phosphorylation; regulation of insulin secretion; regulation of synaptic plasticity; signal transduction; skeletal muscle fiber development; T cell activation; T cell proliferation; regulation of synaptic vesicle endocytosis
Cellular component: calcineurin complex; cytoplasm; cytosol; nucleoplasm; plasma membrane; protein serine/threonine phosphatase complex; glutamatergic synapse; T-tubule; Z disc
Genetic constraint (gnomAD): Loss-of-function variants: 8 observed, 56.73 expected, observed/expected ratio (o/e) 0.14, 90% interval 0.082 to 0.25. The upper end of that interval is the gene's LOEUF score, 0.25, which puts it in group 1 of 6, group 1 being the genes least tolerant of losing a copy. Missense variants: 292 observed, 585.59 expected, observed/expected ratio (o/e) 0.5, 90% interval 0.45 to 0.55. Synonymous variants: 193 observed, 200.52 expected, observed/expected ratio (o/e) 0.96, 90% interval 0.86 to 1.09.
Homologues: Orthologues: dog PPP3CB (99% identical), macaque PPP3CB (99% identical), mouse Ppp3cb (99% identical), pig PPP3CB (98% identical), rat Ppp3cb (97% identical), guinea pig PPP3CB (97% identical), chimpanzee PPP3CB (96% identical), rabbit PPP3CB (95% identical), tropical clawed frog ppp3cc (83% identical), Drosophila melanogaster Pp2B-14D (74% identical), Drosophila melanogaster CanA-14F (73% identical), Drosophila melanogaster CanA1 (71% identical), and 1 more. Paralogues in human: PPP3CA (82% identical), PPP3CC (78% identical), PPEF2 (26% identical), PPP1CA (25% identical), PPP1CC (24% identical), PPP2CB (24% identical), PPP1CB (24% identical), PPP2CA (24% identical), PPEF1 (23% identical), PPP4C (23% identical), PPP5C (23% identical), PPP6C (22% identical).
Diseases named in the same sentence as PPP3CB in open-access papers:
PPP3CB is named in the same sentence as 39 diseases in open-access papers, as found by Europe PMC text mining. Sharing a sentence is not in itself a finding about the gene and the disease. The quoted sentences say what the papers report.
pancreatic cancer (4 papers, 2011 to 2022). "In recent years, it has been reported that PPP1CA, PPP1CB, PPP2CA, PPP2CB, and PPP3CA accelerate the progression of pancreatic cancer, while PPP3CB, PPP5C, and PPP6C hinder PAAD progression." (PMID 34125004, 2021). "PPP3CB showed the most significant prognostic value, with the smallest P-value of 0.0000696, so we further validated this result by immunohistochemistry on pancreatic cancer tissue from an independent cohort of patients." (PMID 33270085, 2021). "Among all the PPPcs, PPP1CB, PPP1CC, PPP2CA, PPP2CB, PPP3CB, and PPP5C had tight associations with at least one of the pancreatic cancer related genes in that list." (PMID 33270085, 2021). "Intriguingly, our work showed that PPP3CA was an unfavorable prognostic factor, but PPP3CB was a favorable prognostic factor for pancreatic cancer." (PMID 33270085, 2021). "In contrast, patients with pancreatic cancer and high transcription levels of PPP3CB, PPP5C, PPP6C, and PPEF2 seemed to have better prognosis." (PMID 33270085, 2021). "Despite few studies of PPP3CB in OS, PPP3CB has been evidenced to correlate with the poor prognosis of neuroblastoma, while PPP3CB might have conducive effects on pancreatic cancer." (PMID 35504036, 2022). "The network analysis revealed a positive link between ERBB2 and PPP3CB, which suggested that PPP3CB might inhibit pancreatic cancer through the ERBB pathway, because the ERBB family are overexpressed in pancreatic cancer and play key roles in its carcinogenesis." (PMID 33270085, 2021). "Results of the present study suggest that PPP1CA, PPP1CB, PPP2CA, PPP2CB, and PPP3CA have deleterious effects but PPP3CB, PPP5C, and PPP6C have beneficial effects on pancreatic cancer." (PMID 33270085, 2021). "Data from THPA and patients with pancreatic cancer enrolled in our hospital also confirmed the prognostic value of PPP1CA, PPP1CB, PPP2CA, PPP2CB, PPP3CA, PPP3CB, and PPP6C at the protein level." (PMID 33270085, 2021). "In addition, only PPP3CB and PPP6C showed favorable prognostic values with regard to protein level, whereas PPP1CA, PPP1CB, PPP1CC, PPP2CA, PPP2CB, and PPP3CA showed unfavorable prognostic values in pancreatic cancer (P<0.05)." (PMID 33270085, 2021). "Among all the PPPcs, the transcription levels of PPP1CA, PPP1CB, PPP3CA, PPP3CB, and PPP4C were higher in pancreatic cancer than in the normal pancreas." (PMID 33270085, 2021).
breast carcinoma (3 papers, 2021 to 2024). "Among the genes with low expression in breast cancer tissues, PPP3CB and PPP6C were positively associated with CD8 + T cell, macrophage and neutrophil infiltration." (PMID 34964699, 2022). "The alterations of PPP1CA, PPP3CA, PPP3CB and PPP6C were significantly associated with the prognosis of breast cancer." (PMID 34964699, 2022). "Collectively, our data demonstrated that p-STAT6 interacted with HDAC1 to repress PPP3CB gene transcription in Herceptin-resistant breast cancer cells." (PMID 33976188, 2021). "However, this negative feedback inhibition is disrupted due to dysregulation of the PPP3CB-FOXO3a-miRNA axis in HER2-positive breast cancer resistant to Herceptin." (PMID 33976188, 2021). "PPP2CB, PPP3CA, PPP3CB, PPP3CC and PPP6C were significantly expressed at lower levels in breast cancer tissues." (PMID 34964699, 2022). "In the Oncomine database, when compared with normal breast tissues, PPP1CA, PPP2CA, PPP4C and PPEF1 were significantly elevated in breast cancer tissues, while PPP1CB, PPP2CB, PPP3CA, PPP3CB, PPP3CC and PPP6C were significantly decreased in breast cancer tissues." (PMID 34964699, 2022). "To explore the molecular basis of PPP3CB downregulation, we first considered an epigenetic mechanism as we showed that a class I histone deacetylase (HDAC) inhibitor, entinostat (SNDX-275 or MS-275) mainly inhibited HDAC1 and potently induced apoptosis in HER2-positive breast cancer cells." (PMID 33976188, 2021).
glioblastoma (3 papers, 2019 to 2024). The most malignant astrocytic tumor (WHO grade IV). "The analysis results of Kaplan-Meier Plotter and SurvExpress showed that high expression of PPP3CB was associated with worse survival in various tumors such as bladder carcinoma, ovarian cancer, gliomas, and glioblastoma (Figure A3)." (PMID 30641937, 2019). "A malignant brain tumor, glioblastoma, is associated with low expression levels of PPP3CB." (PMID 39684750, 2024). "PPP3CB encodes a calcium-dependent protein phosphatase that acts intracellularly on Ca (2+)-mediated signal transduction, and its expression is significantly correlated with human brain aging and glioblastoma multiforme patients’ overall survival." (PMID 35559016, 2022).
neuroblastoma (3 papers, 2019 to 2022). Neuroblastoma (NB) is the most common solid, extracranial childhood tumor. "Similar to the with bioinformatic results, previous research found that high PPP3CB expression was an independent indicator predicting poor prognosis of neuroblastoma (NB)." (PMID 30641937, 2019). "PPP3CB knockdown has decreased cell growth in neuroblastoma cells." (PMID 34366863, 2021).
pancreatic adenocarcinoma (2 papers, 2011 to 2021). "Logsdon demonstrated that the mRNA expression level of PPP3CB had a fold change of 3.002 in patients with pancreatic adenocarcinoma compared with normal tissues." (PMID 33270085, 2021). "The relative abundance of two sense (DAPK1, MAP3K14) and one antisense-oriented (PPP3CB) intronic transcripts in samples of primary pancreatic adenocarcinoma and pancreatic metastases was independently accessed by qRT-PCR, confirming the results measured in the microarray hybridizations." (PMID 22078386, 2011).
asthma (1 paper, 2012). "The identification of PPP3CB, and one of its inhibitors, calcineurin homologous protein (CHP), is of particular interest as PPP3CB/NFAT signaling is implicated in a wide range of biological responses relevant to asthma including lymphocyte activation, as well as neuronal and muscle development." (PMID 22235296, 2012). "PPP3CB (also known as calcineurin) and IGF1 identified by SSH share common signaling pathways also possibly contributing to smooth muscle phenotype switching and ECM remodeling in asthma." (PMID 22235296, 2012).
bipolar disorder (1 paper, 2022). A disorder of the brain that causes unusual shifts in mood, energy, activity levels and the ability to carry out day-to-day tasks. "KLC2, PPP3CB, and CSMD1 were associated with mood disorders such as major depressive disorder or bipolar disorder." (PMID 35559016, 2022).
cardiac hypertrophy (1 paper, 2016). "The predictive activities of the differential trend between PPP3CB and PPP3R1 to the Role of NFAT in cardiac hypertrophy pathway implicated activation of this pathway." (PMID 27907007, 2016). "Therefore, we focused on deciphering and discussing their regulatory roles in cardiac hypertrophy in the following sections and 5 focused NFAT associated genes (PLCE1, PPP3R1, PPP3CB, CAMK1, MEF2C) were studies for experimental validation." (PMID 27907007, 2016). "Notably, the expression patterns of PPP3CB, PPP3R1, PLCE1, MEF2C and CAMK1 in the “NFAT in cardiac hypertrophy” pathway played a significant role in the activation of hypertrophy of atrial myocytes in MR patients compared to normal subjects." (PMID 27907007, 2016).
chromophobe renal cell carcinoma (1 paper, 2024). Chromophobe renal cell carcinoma is a rare subtype of renal cell carcinoma, originating from the intercalating cells of the collecting ducts and macroscopically manifesting as a well-circumscribed, highly lobulated, solid tumor that is usually diagnosed at an early stage. "Similarly, our study identified a copy number variation in the cytoband 10q22.2, which includes PPP3CB, in 33.33% of renal oncocytoma cases, with no such variation observed in chromophobe renal cell carcinoma cases." (PMID 39684226, 2024).
Cognitive impairment (1 paper, 2022). Abnormal cognition is characterized by deficits in thinking, reasoning, or remembering. "CSMD1, PPP3CB, METTL7A, and KLC2 have been reported to be associated with cognitive impairment or cognitive performance." (PMID 35559016, 2022).
injury (1 paper, 2018). Damage inflicted on the body as the direct or indirect result of an external force, with or without disruption of structural continuity. "Astrocyte size and GFAP expression were decreased in brains of Ppp3cb KO mice following photothrombotic stroke or traumatic brain injury." (PMID 29422055, 2018).
lung adenocarcinoma (1 paper, 2024). A carcinoma that arises from the lung and is characterized by the presence of malignant glandular epithelial cells. "A triple osimertinib/calcineurin A/trametinib combination of treatment overcomes acquired resistance to EGFR TKI in EGFR-mutant lung adenocarcinoma cells that overexpress PPP3CB." (PMID 39353739, 2024). "To study whether PPP3CB Ex16 accumulation occurs at disease progression under EGFR TKI treatment, we took advantage of a retrospective cohort of 43 EGFR-mutant lung adenocarcinoma patients with paired tissue sections (pre- and post-progression after EGFR TKI treatment)." (PMID 39353739, 2024).
metastatic tumors (1 paper, 2019). "If the key role of phosphatase activity and direct targeting of PPP3CB are confirmed, it would provide a novel approach (phosphatase inhibitor) and potential molecular target for therapy of metastatic tumors." (PMID 30641937, 2019).
Mitral regurgitation (1 paper, 2022). An abnormality of the mitral valve characterized by insufficiency or incompetence of the mitral valve resulting in retrograde leaking of blood through the mitral valve upon ventricular contraction. "PPP3CB, belonging to α-catalytic subunit gene family members, has been reported to be significantly up-regulated in the atrial myocyte hypertrophy of mitral regurgitation patients." (PMID 36304554, 2022).
Obesity (1 paper, 2018). Accumulation of substantial excess body fat. "We recently showed that mice with a global knockout of Ppp3cb were protected from high fat diet-induced obesity." (PMID 29422055, 2018). "We recently showed that mice lacking the calcineurin subunit A beta (gene name: Ppp3cb) were protected from diet-induced obesity (DIO)." (PMID 29422055, 2018).
psoriasis (1 paper, 2019). An autoimmune condition characterized by red, well-delineated plaques with silvery scales that are usually on the extensor surfaces and scalp. "The MTORC1 gene was up-regulated in the majority of psoriasis patients in the present study, while the opposite genes, PPP3CA and PPP3CB, encoding calcineurin subunits, were down-regulated, which consequently led to reduced mRNA belonging to the MiT family." (PMID 31067781, 2019).
T-cell leukemia (1 paper, 2018). A malignant disease of the T-lymphocytes in the bone marrow, thymus, and/or blood. "To assess whether miR-126-3p was able to regulate these putative target genes, we transfected the T-cell leukemia cell line Jurkat with a miR-126-3p mimic and we evaluated the impact of its ectopic expression on AKT2, PPP3CB, RANKL, and SDC2 transcript levels." (PMID 29850558, 2018).
cancer (11 papers, 2014 to 2024). A tumor composed of atypical neoplastic, often pleomorphic cells that invade other tissues. "PPP3CB encodes the catalytic subunit of calcineurin, a pro-tumorigenic protein whose pharmacological targeting has been reported to have potent antitumor effects in various cancers." (PMID 39353739, 2024). "Two other proteins (CTSP1 and PPP3CB) are protein phosphatases which suppress activation of cancer cells." (PMID 39684750, 2024). "Additionally, both high and low copies of PPP3CB resulted in the reduced expression of effector cells, which indicated that suppressor gene mutation could increase the immune response and further fight against cancer." (PMID 39208654, 2024). "The Pearson Chi-square test showed that the expression of PPP3CB was higher in patients with nuclear grade I to II cancer than those with nuclear grade III cancer (P=0.075)." (PMID 33270085, 2021). "Besides, MS13 treatment in DU 145 and PC-3 cells has shown the downregulation of PPP3CB, TFDP1, SMAD3, and ENDOG, which the anti-cancer activity have not been reported in PCa but noted in other cancers." (PMID 34366863, 2021).
tumor (7 papers, 2011 to 2024). "PPP3CB expression is associated with activation of immune cells which are present in the tumor and expression of immune checkpoint genes to suppress uncontrolled tumor cell growth." (PMID 39684750, 2024). "It has been found that loss of PPP3CB can suppress the tumor growth in vitro and in vivo experiments." (PMID 36187840, 2022). "Besides, in vitro and in vivo experiments indicated that the loss of PPP3CB suppressed the tumor growth." (PMID 30641937, 2019). "Conjoint analysis of the expression pattern and prognosis roles of hub genes demonstrated the oncogenic effect of EGFR and tumor suppressive effect of PPP3CB and MYO5A in GBM." (PMID 30971889, 2019). "Although the majority of the PPP family play important roles in the epithelial-to-mesenchymal transition (EMT) of tumor cells, little is known about the function of PPP3CB in the EMT process." (PMID 30641937, 2019). "Furthermore, analyses of hub genes' prognostic roles demonstrated significant oncogenic effect of EGFR and tumor suppressive effect of PPP3CB and MYO5A in GBM." (PMID 30971889, 2019). "We next explored whether PPP3CB is involved in tumor proliferation." (PMID 30641937, 2019). "Interestingly, although PPP3CB could obviously inhibit the migration of tumor cells and rearrange the cytoskeleton, we also found that PPP3CB promoted tumor cell growth." (PMID 30641937, 2019). "In addition, PPP3CB facilitated tumor cell growth in vivo and in vitro." (PMID 30641937, 2019). "We firstly tested the expression of PPP3CB in normal renal epithelial cells (HK2) and epithelial-like tumor cells (G401)." (PMID 30641937, 2019). "Herein, we demonstrate that PPP3CB overexpression inhibits EMT and migration of G401 cells and promotes tumor proliferation." (PMID 30641937, 2019). "Conversely, overexpression of PPP3CB reversed EMT and inhibited migration of tumor cells." (PMID 30641937, 2019). "We observed that the tumor volume of nude mice which were injected with G401 stable cells without PPP3CB was significantly smaller compared with the control." (PMID 30641937, 2019).
neurodegenerative disease (1 paper, 2022). A disorder of the central nervous system characterized by gradual and progressive loss of neural tissue and neurologic function. "Additionally, PDZRN3 and PPP3CB genes are associated with neurodegenerative diseases, as reported in87,88." (PMID 35705654, 2022).
PPP3CB also shares sentences with these, for which no sentence is quoted: bladder cancer (2 papers); Sepsis (2); acute monocytic leukemia (1); Alzheimer disease (1); amyotrophic lateral sclerosis (1); aortic valve disease (1); cardiomyopathies (1); Ductal carcinomas (1); glioma (1); Hydrocephalus (1); major depressive disorder (1); malignant brain tumor (1); mood disorder (1); neurodevelopmental disorder (1); neurological diseases (1); ovarian carcinoma (1); prion disease (1); renal oncocytoma (1); Stroke (1).